BRCA2 (BRCA2 DNA repair associated)
Diseases named in the same sentence as BRCA2 in open-access papers (continued):
Sharing a sentence is not in itself a finding about the gene and the disease.
breast cancer (continued). "Recently, deleterious mutations in 14 known breast cancer susceptibility genes including BRCA1, BRCA2, and RAD51C were identified at a frequency of 3.7 % in a large series of 1,824 patients with TNBC unselected for family history of breast cancer." (PMID 27553291, 2016). "Previously, we had identified 11 BRCA carriers in a series of 40 selected breast cancer patients at increased risk for carrying a mutation in the BRCA1 and BRCA2 genes." (PMID 27129401, 2016). "Expression of BRCA1 and BRCA2 in CMT was analyzed and it was found to be associated with an increased mammary tumor risk in English Springer Spaniels (ESS)." (PMID 27657059, 2016). "The estimated lifetime risk of breast cancer is 1–5 % in male BRCA1-mutation carriers and 5–10 % in male BRCA2-mutation carriers versus 0.1 % in the general population." (PMID 27377827, 2016). "Several genes predisposing to breast cancer have been identified, including BRCA1 and BRCA2, which explain about 20% of the familial breast cancer cases." (PMID 27158822, 2016). "The risk of breast cancer by the age of 70 years has been reported as 57%-65% when there was BRCA1 mutation and 45%-49% when there was BRCA2 mutation." (PMID 27643881, 2016). "Here, we describe the generation of a novel mouse model that has a single amino acid alteration in the BRCA2 protein that affects its interaction with another hereditary breast cancer protein, PALB2." (PMID 27490902, 2016). "In BRCA1/BRCA2 mutation carriers, PBSO/RRSO not only decreases the risk of development of ovarian cancer by 80-90 % and breast cancer by 40–50 %, but also reduces mortality due to cancer of the genital tract and overall mortality." (PMID 26928677, 2016). "About 10% of all breast cancers arise from hereditary mutations that increase the risk of breast and ovarian cancers; and about 25% of these are associated with the BRCA1 or BRCA2 genes." (PMID 28009814, 2016). "Germline mutations in breast cancer susceptibility genes BRCA1 and BRCA2 confer a high risk of breast and ovarian cancer." (PMID 27257965, 2016). "Susceptibility to breast cancer can involve the tumor suppressors breast cancer-1 (BRCA1) and breast cancer-2 (BRCA2), which are also involved in ovarian cancer." (PMID 26840090, 2016). "While BRCA1 and BRCA2 mutations affect a minority of breast cancer patients (fewer than 5%), BRCA1 and BRCA2 were silenced by promoter region hypermethylation in 9% and 2% of sporadic breast cancer, respectively." (PMID 26967246, 2016). "We analyzed through array CGH the genomic profile of 47 biopsies, from hereditary breast cancer patients, 40 from BRCAX patients, 3 from BRCA1 and 4 from BRCA2 mutation carriers." (PMID 26979459, 2016). "Among the genes down-regulated in this GO term were transcriptional repressors of immune system such as ZFAT (Zinc Finger Protein 406, FC = 2.4); BRCA2 (Breast Cancer 2, Early Onset, FC = 3.2), and ZNF160 (Zinc Finger Protein 160, FC = 2.5)." (PMID 27427759, 2016). "The most common genetic marker examined for potential breast cancer cases is the breast cancer susceptibility 1 (BRCA1) and 2 (BRCA2) genes." (PMID 30460281, 2016). "A total of 40 breast cancer patients have been studied for germline mutation in both BRCA1 and BRCA2 genes to contribute to the clarifying of this situation; the entire BRCA1/2 were analyzed using a direct sequencing." (PMID 26997744, 2016). "It should also be noted that we have studied only a small portion of possible mutations (5382insC, 4153delA, 185delAG and 300T> G in the BRCA1 gene, and 6174delT in the BRCA2 gene) in women with breast cancer in Uzbekistan." (PMID 29138730, 2016).
breast cancer (continued). "The results showed that certain genotypes of VNTR polymorphisms are associated with the risk of familial breast cancer in BRCA1+ and BRCA2+ carriers." (PMID 27148484, 2016). "Approximately 5–10% of female breast cancer are believed to be hereditary, caused by a germline mutation in the BRCA1 or BRCA2 genes." (PMID 27566577, 2016). "Mutations in the two major high-penetrance breast cancer genes, BRCA1 (breast cancer 1, early onset gene) and predominantly BRCA2 (breast cancer 2, early onset gene), account for approximately 10 % of MBCs outside populations with BRCA founder mutations." (PMID 26857456, 2016). "Early age of onset for breast cancer can reflect a genetic predisposition in particular mutations of BRCA1 and BRCA2 genes." (PMID 27770782, 2016). "The breast cancer susceptibility genes, BRCA1 and BRCA2, are responsible for a high proportion of cases of hereditable breast cancer." (PMID 27377827, 2016). "Less than 20 % of familial breast cancer patients who undergo genetic testing for BRCA1 and BRCA2 carry a pathogenic mutation in one of these two genes." (PMID 26758370, 2016). "Genetic predisposition can be the cause of breast cancer and germline mutations in the two major breast cancer susceptibility genes BRCA1 and BRCA2 confer highly elevated risk of the disease." (PMID 27357824, 2016). "This dataset contains 359 patients with breast cancer, among which there were 22 BRCA1 mutation cases, 32 BRCA2 mutation cases and 305 sporadic cases." (PMID 27566577, 2016). "About 40-60 % of hereditary breast and ovarian cancers (HBOC) are due to the presence of germline mutations in the breast cancer susceptibility genes type 1 and 2 (BRCA1 and BRCA2)." (PMID 27391110, 2016). "Recently it has been discussed that disproportional distribution of the mutation of the BRCA2 gene in the geothermal population as compared to the reference populations in previous studies may be a confounding factor, in particular for the association with breast cancer among women." (PMID 27205903, 2016). "We have previously shown that the known human breast cancer genes BRCA1, BRCA2 and ESR1 are associated with CMT in ESS dogs overlapping with this cohort, although not as strongly as the risk factors identified in this GWAS study." (PMID 27158822, 2016). "The age of diagnosis of breast cancer in the BRCA2 carriers ranged from 47 to 78 years old with a median age of 65 years." (PMID 27532258, 2016). "Breast cancers arising in the setting of the hereditary breast cancer genes BRCA1 and BRCA2 are most commonly classified as basal-like breast cancer (BLBC) or luminal breast cancer, respectively." (PMID 27708239, 2016). "PALB2 has recently been reported to confer a breast cancer risk comparable to that of BRCA2 mutations, indicating the need to include it in the clinical diagnostics along with BRCA1 and BRCA2 mutation testing." (PMID 26820313, 2016). "Germline mutations in DNA mismatch repair genes (BRCA1, BRCA2, CHEK2, ERCC4, FAAP100, and TP53BP1, amongst others) are associated with breast cancer susceptibility." (PMID 27608040, 2016). "Our study provides evidence showing that VNTR polymorphisms in the XRCC5 promoter is associated with risk of familial breast cancer with BRCA1+ and BRCA2+ predisposition." (PMID 27148484, 2016).
breast cancer (continued). "Management of women who are considered high-risk for the development of breast cancer is controversial, especially in women who carry a BRCA1 or BRCA2 mutation as they can develop cancers at an earlier age." (PMID 28133583, 2016). "In our previous study, we reported that the most common recurrent mutations in Chinese women at high risk for breast cancer are c.5470_5477del8 in BRCA1 and c.3109C > T in BRCA2, which were reported to be the putative founder mutations." (PMID 26852015, 2016). "All told, 5 % of all breast cancer cases and up to 25 % of familial breast cancer cases can be attributed to high-penetrance mutations in BRCA1 and BRCA2." (PMID 27716388, 2016). "This is presumed to be why many reports on the effects of early diagnosis on inherited breast cancer have combined BRCA1 and BRCA2 mutation carriers together to provide sufficient enough cases to arrive at a significant conclusion." (PMID 27087880, 2016). "Analysing the largest series of BRCA1 and BRCA2 breast cancers collected to date from both sexes, we have demonstrated that breast tumours arising in BRCA1 and BRCA2 mutation carriers display pathologic differences between males and females." (PMID 26857456, 2016). "Although caused by genes involved in homologous DNA repair, breast cancers caused by BRCA1 and BRCA2 mutations appear to be rather different diseases." (PMID 27087880, 2016). "About 15% of women with familial breast cancer are implicated to have mutation in BRCA1 and BRCA2 genes, also, all women with ovarian cancer are affected by some mutation in these genes." (PMID 27351029, 2016). "RAD51 forms a complex BRCA2 (breast cancer 2), which becomes activated by phosphorylation after DSB, enabling the binding of RAD51 to ssDNA." (PMID 26784176, 2016). "In breast cancer, forexample, BRCA1 and BRCA2 are susceptibility genes thataccount for around 25% of families with hereditary breast cancer." (PMID 27192130, 2016). "At the age of 70 years old, the mean cumulative breast cancer risks for BRCA mutation carriers are 47%-66% (BRCA1) and 40%-57% (BRCA2) in western countries." (PMID 27257965, 2016). "Recently a Dutch group showed no improvement in survival, based on only two deaths out of 18 BRCA2 related breast cancers compared to three events in controls." (PMID 27087880, 2016). "The main aim of this study was to screen the male patients with breast cancer for BRCA1 and BRCA2 mutations as well as the status of tissue tumor markers including ER, PR, HER-2 and basal marker (CK5/6)." (PMID 27478808, 2016). "Equol modulates expression of the BRCA1 and BRCA2 breast cancer genes through an epigenetic mechanism resulting in decreased methylation, which results in an increased level of oncosuppressors in breast cancer cell lines." (PMID 28149839, 2016). "SNPs in genes involved in the BER pathway have been reported to modify ovarian and breast cancer risk in BRCA1 and BRCA2 mutation carriers." (PMID 27015555, 2016). "We reveal a DNA binding domain in the N terminus of BRCA2 that can stimulate RAD51-mediated homologous recombination and is mutated in breast cancer patients." (PMID 27628236, 2016). "High penetrance inherited breast cancer is mainly caused by pathogenic mutations in the BRCA1 and BRCA2 genes." (PMID 27087880, 2016).
breast cancer (continued). "Five BRCA mutation-positive patients had a second cancer: two previously had breast cancer (both BRCA1 mutation carriers), one previously had melanoma and two had synchronous endometrial cancer (all BRCA2 mutation-carriers)." (PMID 27406733, 2016). "BRCA2 status was established on average six years post breast cancer diagnosis in the controls, with a median time of 4.7 years." (PMID 27087880, 2016). "A study from the British population showed that rs1799796 decreases the risk of breast cancer while another study from Belgium reported an increased risk associated with this SNP in BRCA1 and BRCA2 carriers." (PMID 26881229, 2016). "Clinically actionable mutations in BRCA1, BRCA2 and ERBB2(HER2) were detected in 5.5% of patients, while 53% had genomic alterations matching ongoing or concluded breast cancer studies." (PMID 27901097, 2016). "This is further exemplified by use of PARP inhibitors to exploit the DNA repair defect of BRCA1 and BRCA2 mutant breast cancers." (PMID 26943587, 2016). "According to literature, the average cumulative risks of developing breast cancer for BRCA1 and BRCA2 mutation carriers by the age of 70 years are 65% and 45%, respectively, and those of ovarian cancer are 39% and 11%, respectively." (PMID 26997744, 2016). "The increased risk for breast cancer is associated, among others, with a personal or family history of the disease and inherited gene mutations in BRCA1 and BRCA2 breast cancer susceptibility genes." (PMID 27974927, 2016). "For women, the risk of developing breast cancer by age 70 is approximately 60–70% for BRCA1 and 45–55% for BRCA2 mutation carriers." (PMID 27375968, 2016). "We show, using human lung, ovarian, and breast cancer cell lines, that BRCA2 ASO treatment can overcome innate resistance to olaparib in these cell lines." (PMID 26959114, 2016). "Hereditary breast cancer arising in the setting of germline mutations in BRCA1 and BRCA2 is recognized to generally sort with the BLBC and luminal subtypes of breast cancer, respectively." (PMID 27708239, 2016). "TOP1 overexpression was mostly observed in BRCA1-related (60%) and in BRCA2-related breast carcinomas (59%) as compared to sporadic breast carcinomas (35%)." (PMID 27566577, 2016). "AICAR showed biological activity in human cells by selective inhibition of growth of BRCA1-deficient HCC1937 breast carcinoma cells, BRCA1-deficient BCR-ABL1-positive leukemia cells, and BRCA2-deficient Capan-1 pancreatic adenocarcinoma cells." (PMID 27649245, 2016). "Chang and colleagues also reported a null association with all‐cause death in a cohort of BC patients in the Breast Cancer Family Registry in Northern California, USA when excluding those with BRCA1 and BRCA2 mutation." (PMID 26799372, 2016). "Of note, the rates of TOP1 and CDH3 positivity were the highest in BRCA1-related breast carcinomas (48%) followed by BRCA2-related (24%) and sporadic breast carcinomas (7%)." (PMID 27566577, 2016). "With regard to CDH3, a significant difference was found among the three groups with 76% of BRCA1-related, 37% of BRCA2-related and 22% of sporadic breast carcinomas being CDH3 positive (p < 0.001)." (PMID 27566577, 2016). "Protein expression of CDH3 and TOP1 was analysed in a panel of 253 human breast carcinomas comprising 102 BRCA1-related, 49 BRCA2-related and 102 sporadic breast carcinomas." (PMID 27566577, 2016). "Since it became evident that only 15%-20% of the familial risk for BC/OC can be explained by mutations in the major breast cancer-susceptibility genes BRCA1 and BRCA2, the search for additional BC/OC susceptibility loci has been pursued." (PMID 27504877, 2016). "On the other hand, depletion of the tumor suppressor gene BRCA2 results in downregulation of UbcH8 in breast cancer cells." (PMID 26506425, 2015).
breast cancer (continued). "The existence of a family history of breast cancer is one of the strongest risk factors, and the known pathogenic mutations in the BRCA1 and BRCA2 genes confer a life-time risk of breast cancer of 60–85% and 55–85%, respectively." (PMID 25339628, 2015). "Researchers have established that these genes can also be involved in the development of non-hereditary, sporadic tumours, as a proportion of ovarian and breast cancers contain somatic (tumour only) BRCA1 and BRCA2 pathogenic variants." (PMID 25859162, 2015). "The BRCA2 c.7934delG Afrikaner founder mutation was identified in 2 (white) patients, one with TNBC and one diagnosed with premenopausal breast cancer." (PMID 26577449, 2015). "We found that BRCA2 expression was significantly reduced in mammary tumor samples compared to mammary gland samples." (PMID 26202431, 2015). "Today, the prevention of breast cancer among BRCA1 and BRCA2 mutation carriers has focused on surgical options such as risk-reducing bilateral mastectomy and bilateral salpingo-oophorectomy." (PMID 26496879, 2015). "In this study, we investigated the effects of PARP inhibitors in BRCA1 or BRCA2 mutant breast cancer cell lines and in wild-type BRCA cell lines with and without BRCA1 allelic loss." (PMID 25975349, 2015). "For BRCA1 and BRCA2 there was a tendency towards a worse breast cancer-specific and overall survival, however, results were heterogeneous and the evidence was judged to be indecisive." (PMID 25816289, 2015). "As expected, the BRCA2 expression level in canine mammary tumors was significantly lower than the level in normal mammary gland tissues." (PMID 26202431, 2015). "This study aimed to evaluate the contribution of germline BRCA1, BRCA2 and PALB2 mutations and the CHEK2 c.1100delC allele to breast cancer in a high-risk South African cohort." (PMID 26577449, 2015). "French Canadian breast cancer and breast-ovarian cancer syndrome families of the province of Quebec harbour specific BRCA1 and BRCA2 mutations that recur in this demographically unique population due to founder effects attributed to common ancestors." (PMID 25884701, 2015). "Several studies have shown that the morphological and immunohistochemical phenotypes of BRCA1- and BRCA2-related breast cancers differ from that of sporadic breast cancers." (PMID 26496879, 2015). "Many of these genes have known roles in cancer gene networks such as the proto-oncogenes JUN and FOS, RAP1A (RAS-related protein 1A), ITGB5, as well as BRCA2 (Breast cancer 2, early onset) and PCNA (Proliferating cell nuclear antigen)." (PMID 26448646, 2015). "Due to the substantial risk of breast cancer conferred by the BRCA1 and BRCA2 mutations, development of prevention strategies for mutation carriers is imperative." (PMID 26496879, 2015). "Overall, these results show that BRCA1-deficient tumors are significantly enriched for indels in BRCA1 TR genes compared to BRCA2 and sporadic breast cancers." (PMID 25699710, 2015). "BRCA2 (breast cancer 2, early onset), identified in 1994, is a tumor suppressor that functions in homologous recombination and double-stranded DNA repair." (PMID 26380221, 2015). "Approximately 5–10% of breast cancers and 10% of ovarian cancers have a hereditary component, which in most cases is associated with clinically significant mutations in the BRCA1 and BRCA2 genes." (PMID 25948282, 2015). "With regard to breast cancer, PLCG2 has been identified as an irradiation-responsive gene and a potential modifier of breast cancer risk in BRCA2-mutation carriers." (PMID 26275715, 2015). "BRCA2 mRNA levels were compared between seven mammary gland samples and seventeen mammary tumor samples isolated from dogs." (PMID 26202431, 2015). "Majority of the known breast cancer susceptibility genes have a role in DNA repair and the most important high-risk genes BRCA1 and BRCA2 are specifically involved in the homologous recombination repair (HRR) of DNA double-strand breaks." (PMID 25918678, 2015).